IGF2 (insulin like growth factor 2)
Diseases named in the same sentence as IGF2 in open-access papers (continued):
Sharing a sentence is not in itself a finding about the gene and the disease.
breast tumor (18 papers, 2011 to 2024). "Hypermethylation of IC1 and pUPD11 result in upregulation of the biallelic expression of IGF2, which has been associated with tumorigenesis in various subtypes of breast tumors." (PMID 38514513, 2024). "IGF-2 expression is also increased locally in breast tumors through loss of imprinting, and its function is enhanced by loss of heterozygosity at the IGF2R locus." (PMID 36556357, 2022). "Transgenic overexpression of IGF2 increases the risk of developing lung and breast tumors in mice while transgenic mice homozygous for a disruption of the Igf2 gene develop tumors with reduced malignancy." (PMID 34440844, 2021). "Gene expression analysis of isolated cell populations revealed that TAMs are the main source of Igf-1 and that both TAMs and cancer-associated fibroblasts (CAFs) are major sources of Igf-2 in the breast tumor microenvironment." (PMID 29367764, 2018). "GDF15 was implicated in multiple cancer types and correlates with lymph node metastases in endometrial cancer and overexpression of IGF-2 or PTGS2 mRNAs in breast tumors associated with greater mortality and increased metastatic potential." (PMID 26910917, 2016). "Several mechanisms may lead to increased expression of insulin-like growth factor-2 (IGF2) in patients with BWS, and IGF2 has been associated with tumorigenesis in various breast tumors; however, few reports have described fibroadenomas in patients with BWS." (PMID 38514513, 2024). "Overexpression of IGF2, which may be associated with the occurrence of breast tumors, was confirmed in the present case, and the patient’s clinical features and overexpression of IGF2 allowed speculation regarding the specific subtype of molecular defect." (PMID 38514513, 2024). "In vivo results demonstrated that the expression of the Igf2r transgene delays breast tumor onset and decreases tumor multiplicity in Igf2 transgenic mice." (PMID 34440844, 2021). "IGF2 is also highly expressed in BC patients and “free” circulating IGF2 levels in humans are significantly correlated with breast tumor size." (PMID 33216823, 2020). "Immunofluorescent staining of αSMA and Ki67 in the murine breast tumors showed that αSMA+ stromal cells, which appear to be a major source of IGF-2, also surround actively dividing tumor cells." (PMID 29367764, 2018). "Independent investigators have also identified IGF2 as a key factor in the genesis of breast tumor spheres." (PMID 29099049, 2017). "Correlation of increased IMP1 expression with the reduced levels of its bound mRNAs, such as PTGS2, GDF15 and IGF-2 transcripts, was also observed in human breast tumors." (PMID 26910917, 2016). "Furthermore, “free” circulating IGF2 levels in humans are significantly correlated to breast tumor size and malignancy." (PMID 33216823, 2020). "Analysis of 965 primary breast tumors from TCGA RNA‐seq dataset showed that breast tumors harboring H1047R and other PIK3CA mutations (including E545K and E542K) have significant upregulation of AXIN2, HGF, STAT3, IGF‐1, and IGF‐2 mRNA compared with PIK3CA‐wild‐type and HER‐2‐amplified tumors." (PMID 28296140, 2017). "In addition, higher IMP1 protein levels correlated with lower expression of GDF15, PTGS2 and IGF2 mRNAs in human breast tumors." (PMID 26910917, 2016). "IGF-2 is a secreted protein highly expressed in breast tumor tissue." (PMID 25874233, 2015). "There are also reports of altered IGF2 methylation in breast tumours." (PMID 26347357, 2015). "It was recently shown that a long non-coding RNA (lncRNA), that we named the 91H RNA (i.e. antisense H19 transcript), is overexpressed in human breast tumours and contributes in trans to the expression of the Insulin-like Growth Factor 2 (IGF2) gene on the paternal chromosome." (PMID 22662250, 2012). "In human breast tumors, IMP1 mRNA could be post-transcriptional regulated and its expression seemed to be correlated with the reduced levels of its associated transcripts, such as PTGS2, GDF15 and IGF-2 mRNAs." (PMID 26910917, 2016).
breast tumor (continued). "In this case, overexpression of IGF2 suggested a possible relationship between BWS and breast tumors." (PMID 38514513, 2024). "We recently showed that TAMs and CAFs are the main sources of Insulin-like growth factors 1 and 2 (IGF-1, IGF-2) in pancreatic and breast tumors, and that IGF signaling mediates resistance of murine pancreatic and breast tumors to gemcitabine and paclitaxel." (PMID 30356656, 2018). "IGF2 expression is reportedly more upregulated in breast tumors including fibroadenoma than in non-neoplastic mammary grand tissue." (PMID 38514513, 2024). "In view of the fact that IGF1 is mainly produced by stromal cells whereas IGF2 biosynthesis occurs directly in breast tumor cells, data indicate that BRCA1 gene expression is potentially regulated by both autocrine (IGF2) and paracrine/endocrine (IGF1) stimuli." (PMID 35432218, 2022). "In multiple in vivo breast tumor models, non-immune stromal cells and tumor-associated macrophages (TAM), but not tumor cells, primarily express Igf1 and Igf2 mRNA." (PMID 36556357, 2022). "Since the P values for IGF2 mRNA was not significant (P > 0.1), the results suggested a positive connection between increased levels of IMP1 and reduced expression of GDF15 and PTGS2 mRNAs in human breast tumors." (PMID 26910917, 2016).
Cognitive impairment (18 papers, 2013 to 2024). Abnormal cognition is characterized by deficits in thinking, reasoning, or remembering. "Several studies have shown in an animal model that IGF2 treatment enhances memory functions and reverses cognitive impairment, motor deficits, and seizures in affected mice." (PMID 36673541, 2023). "In rodent models of AD, exogenous IGF2 can in some cases ameliorate cognitive impairments, neuropathological changes, and neurotrophic decline." (PMID 36971212, 2023). "On the other hand, IGF2 has been shown to ameliorate synaptic deficits, and cognitive impairments in AD transgenic mice." (PMID 38042807, 2023). "IGF2 depletion accelerates the onset of metabolic deficits, reduced cell survival, and cognitive impairments by altering growth hormone-related gene expression." (PMID 36739453, 2023). "It was shown that IGF-2 treatment restores some cognitive impairments in mouse models of schizophrenia (Dgcr8+/−) and AD (Tg2576)." (PMID 33673334, 2021). "In CSF, IGF2 has been identified as a marker of mild cognitive impairment in Alzheimer’s patients and as a biomarker for the progression of amyotrophic lateral sclerosis." (PMID 33668197, 2021). "The purpose of this study was to assess the levels of serum IGF-2 and its binding proteins IGFBP-3 and IGFBP-7 in schizophrenia patients and the associations of these proteins with schizophrenia psychopathology and cognitive deficits." (PMID 32191705, 2020). "Injection of IGF2, a molecule that induces mTOR signaling, could fully rescue cognitive impairment and IEG expression in aging Tsc2+/− animals." (PMID 39192595, 2024). "In a rat model of age‐related cognitive decline, reduced IGF2 expression in the synaptic compartment was associated with cognitive deficits even as overall IGF2 expression showed no apparent decline." (PMID 36971212, 2023). "In the Angelman syndrome mouse model, Ube3am-/p+, systemic administration of IGF-2 significantly attenuated acoustically induced seizures and restored cognitive impairments assessed by measurements of contextual and recognition memories, motor deficits and working memory." (PMID 33673334, 2021). "Because IGF1 and IGF2 activate the same receptor, IGF2 may have some utility in reversing some of the cognitive deficits in PTHS patients." (PMID 24058414, 2013). "Furthermore, the therapeutic utility of IGF2 may also extend to the prevention of AD in patients who have yet to manifest cognitive impairment." (PMID 36971212, 2023). "Thus, Igf2 deletion results in the differentiation of neural stem cells into neurons, leading to hyposmia, due to an increase in the number of neurons in the olfactory bulb, together with cognitive deficits and increased anxiety." (PMID 35741015, 2022). "Given that IGF-2 is abundantly expressed in brain regions that are relevant to working memory and executive function, like hippocampus and prefrontal cortex, these findings demonstrate that abnormal IGF-2 signaling is implicated in cognitive impairments of schizophrenia." (PMID 32191705, 2020). "However, thus far, whether there is a relationship between IGF-2 signaling and the psychopathology and cognitive impairments in schizophrenia remains unknown." (PMID 32191705, 2020). "The effect of cognitive impairment on plasma levels of BDNF, 3-NT, IGF-1, IGF-2 and IGFBP-3 was evaluated using Student’s t test." (PMID 34341419, 2021). "IGF-2 and m6p were also found to be interchangeable for IGF2R-mediated effects in reversing the cognitive impairment in the model of Angelman syndrome." (PMID 33673334, 2021). "There is substantial variation in circulating IGF2 among healthy adults (300–1100 ng/mL122), but this natural variation does not appear to correlate with AD status or degree of cognitive impairment." (PMID 36971212, 2023).
Cognitive impairment (continued). "Our results indicate that IGF-2, administered in the chronic stage of injury, is ineffective at enhancing memory performance and therefore may not be a beneficial treatment option for lingering cognitive impairments after a TBI." (PMID 34901941, 2021). "Our study demonstrates that serum IGF-2 was significantly correlated with negative and cognitive symptoms in patients with schizophrenia, suggesting that altered IGF-2 signaling may be implicated in the psychopathology and cognitive deficits in schizophrenia." (PMID 32191705, 2020). "Few cognitive studies have been performed in SRS patients with low levels of IGF2 expression, and one study showed that SRS patients did not actually present cognitive deficits relative to a control population, but that they had a smaller frontal and parietal lobe volume in the brain." (PMID 35741015, 2022).
metabolic syndrome (18 papers, 2013 to 2025). A cluster of metabolic risk factors for CARDIOVASCULAR DISEASES and TYPE 2 DIABETES MELLITUS. "It is known that the level of IGF2 protein in the blood serum is considerably higher in patients with metabolic syndrome, and the level of expression of the gene encoding IGF2 is also increased in obese mice on a high-calorie diet." (PMID 34360859, 2021). "The hypermethylation level of DNMT3a and insulin-like growth factor 2 (IGF2) genes may increase the risk of metabolic syndrome in Chinese adults by affecting ELOVL6 activity dependence." (PMID 39200098, 2024). "Thus, individuals prenatally exposed to famine during the Dutch Hunger Winter had reduced glucose tolerance and increased risk for metabolic syndrome and showed less DNA methylation of the imprinted insulin-like growth factor 2 (IGF2) gene even six decades later." (PMID 37296584, 2023). "Exposure to a high-fat diet in utero might cause a metabolic syndrome-like phenomenon through epigenetic modifications of the expression of insulin-like growth factor 2 (IGF2), a candidate in developmental programming and determinant of later adult disease risk." (PMID 25875118, 2015). "On the other hand, lower IGF-2 levels were observed in patients suffering from metabolic syndrome compared to healthy subjects." (PMID 34063412, 2021). "Thus, among other modifications, a reduction was found in DNA methylation in famine-exposed offspring compared to same-sex controls, on the promoter of the insulin-like growth factor 2 (IGF2) gene that modulates foetal development and growth, and is implicated in metabolic syndrome." (PMID 35052371, 2021).
gestational diabetes mellitus (17 papers, 2012 to 2025). "Furthermore, dysregulated expressions of several imprinted genes (e.g., Igf2, Phlda2, H19 and Gab1) in the placenta have been implicated in various pregnancy complications, including preeclampsia, gestational diabetes and FGR." (PMID 40550626, 2025). "Interestingly, specific fetal IGF2 paternal haplotypes are linked to higher maternal glucose levels that increase the risk of gestational diabetes." (PMID 24454871, 2014). "Elevated IGF2 concentrations were associated with higher birth weight (p < 0.0001) after adjusting for maternal race/ethnicity, pre-pregnancy BMI, cigarette smoking, gestational diabetes, and infant sex." (PMID 22392079, 2012). "Dysregulation of imprinted genes, including Igf2, Phlda2, H19 and Gab1 has been observed in placentas affected by pregnancy complications including preeclampsia, gestational diabetes and FGR." (PMID 40550626, 2025). "The expression of IGF2 is significantly higher in gestational diabetes mellitus, while the expression of H19 is significantly lower in GDM." (PMID 35563893, 2022). "In addition, modified expression of Igf2 and H19 genes was demonstrated in the sperm of adult F1 offspring of female mice with gestational diabetes." (PMID 28750655, 2017). "The study on gestational diabetes mellitus (GDM) mice showed that the pups demonstrated hypermethylation and epigenetic downregulation of IGF2 and H19 genes involved in insulin sensitivity." (PMID 37298715, 2023). "Interestingly, the patients of both groups exhibited almost identical expression levels, meaning that IGF2 and GRB10 genes are maintained at similar levels in healthy and in gestational diabetes patients." (PMID 35454338, 2022).
glioma (17 papers, 2011 to 2026). A benign or malignant brain and spinal cord tumor that arises from glial cells (astrocytes, oligodendrocytes, ependymal cells). "Finally, elevated expression of IGF-1R and IGF2 in gliomas associated with poor patient survival and tumor expression levels of IGFBP6 directly correlated with overall survival time in patients with GBM." (PMID 30231881, 2018). "In the first dataset, IGF2 was highly expressed in a subset of glioma cells, whereas the IGF2 receptors were highly expressed in TME cell types, including endothelial cells, pericytes, oligodendrocytes, and myeloid cells." (PMID 41568176, 2026). "IGF1, on the other hand, was most expressed in myeloid and immune cells, validating our findings in mBT0309 that glioma cells express IGF2 to a greater degree." (PMID 41568176, 2026). "To further understand how the Igf2 amplified glioma model, mBT0309, shapes the TME over time, we performed multiplex IMC using a custom 33-antibody neuro-immuno-oncology panel on a time course of tumor development." (PMID 41568176, 2026). "In A172 glioma cells, mRNA levels of IGF2, Gli1, and Myc were significantly downregulated in Lnc-THOR-silenced or Lnc-THOR-KO A172 cells." (PMID 31727877, 2019). "We have characterized a population of chemoresistant glioma cells in which AKT is activated through the binding of IGF2 to IGF-1R and indirectly repressed by IGFB6 secreted from chemosensitive glioma cells." (PMID 30231881, 2018). "Our observations suggest that IGF-1R/IGF2 can be considered a potential target for the treatment of chemoresistant gliomas." (PMID 30231881, 2018). "As a positive control for the in vivo binding of CTCF, we performed a ChIP assay in U87MG glioma cells using primers from the Imprinting Control Region of the human Igf2/H19 imprinted locus, which is known to have several CTCF binding sites." (PMID 21663659, 2011). "Interestingly, genes involved in gliomas development (IGF2, H19, PHLDA2/TSSC3, TRIM3, SLC22A18) are located in the gene locus 11p15.5 of the beta hemoglobin chain." (PMID 32183175, 2020). "Thus, IGF2 secreted by TMZ-resistant glioma cells appears to function in an autocrine manner, phosphorylating IGF-R1 expressed by the TMZ-resistant cells." (PMID 30231881, 2018). "Early studies comparing normal brain and mixed glioma specimens largely indicated elevated tumour IGF1 and IGF2 expression and protein abundance; however, these reports suffered from ambiguity due to small sample sizes and differing detection methods." (PMID 40429889, 2025). "To validate IGF2 gene induction by rHSVQ infection in our preclinical models, we performed qRT-PCR analysis of various primary GBM, BC, and murine glioma cells following rHSVQ infection." (PMID 38853689, 2024). "In glioma, overexpression of PIK3R3 can support the growth of GBM cells by engaging IGF2 signaling in vitro, indicating that PIK3R3 is an oncogene in glioma." (PMID 34961815, 2021). "Here, we show that TMZ-resistant and TMZ-sensitive glioma cells co-exist within GBM tumors, and the interaction of these cells through the secretion of IGF2 and IGFBP6, respectively, regulates cell proliferation and growth of the tumor." (PMID 30231881, 2018). "A subset of human gliomas appears to express IGF1 and/or IGF2, and evidence suggests that IGF2 contributes to the aggressive nature of some GBMs." (PMID 30231881, 2018). "Our results do not however address the origins of heterogeneity, and leave open the issue of how amplified IGF2+/IGF-1R+ and IGFBP6+ subpopulations arise during the establishment of a glioma." (PMID 30231881, 2018). "Since TMZ-sensitive glioma cells produce IGFBP6, we evaluated the effects of conditioned medium from TMZ-sensitive U251 cells on IGF2-dependent phosphorylation of IGF-1R and AKT expressed by TMZ-resistant UTMZ glioma cells." (PMID 30231881, 2018).
glioma (continued). "IGF2 mRNA-binding protein 3 (IMP3), a GBM upregulated RNA binding protein, promotes glioma cell migration." (PMID 28465487, 2017). "Therefore, we tested the effect of IGF2 on the phosphorylation of IGF-1R and AKT in TMZ-sensitive and TMZ-resistant glioma cells." (PMID 30231881, 2018). "We determined that in human glioma tissue, glioma cell lines, and patient-derived xenograft cell lines, treatment with TMZ enhances the expression of IGF1 receptor (IGF-1R) and IGF2 and decreases the expression of IGFBP6, which sequesters IGF2." (PMID 30231881, 2018). "Importantly, systemic delivery of an IGF2-neutralizing antibody failed to improve therapeutic efficacy of rHSVQ in intracranial 005 murine glioma and DB7 BCBM tumors, likely due to the inability of the antibody to penetrate the blood-brain barrier (BBB)." (PMID 38853689, 2024). "While most human glioma cell lines do not express IGFs, a subgroup of human gliomas were reported to express IGF1 and/or IGF2, indicating a possible autocrine component." (PMID 30231881, 2018).